AVP (arginine vasopressin)
Diseases named in the same sentence as AVP in open-access papers (continued):
Sharing a sentence is not in itself a finding about the gene and the disease.
Anxiety (continued). "However, AVP also modulates various social and anxiety-related behaviors by its actions in the brain, often sex-specifically, with effects typically being stronger in males than in females." (PMID 36860367, 2023). "This may explain the conflicting effects of AVP agonists/antagonists injected into PVN on anxiety-like behavior." (PMID 36860367, 2023). "However, in the more social zebra finch, knockdown of BNST AVP reduces preference for larger flocking groups (gregariousness), and increases anxiety-like behavior." (PMID 36860367, 2023). "OXT and AVP are also critical regulators of anxiety and depression-like behaviors." (PMID 36430254, 2022). "Depression with above-normal plasma AVP, as well as familial depression with above-normal plasma AVP, showed a high correlation between anxiety and retardation and this correlation was significantly higher than that found in the depressed patient control groups." (PMID 36004833, 2022). "Acute i.c.v administration of AVP causes increased scratching and grooming (behaviors related with stress and anxiety) in wild type but not in V1A receptor-knockout mice." (PMID 36569629, 2022). "In the brain, AVP serves as a neuromodulator that regulates a variety of physiological functions including social behaviors, learning and memory, nociception, circadian rhythms, and neurologic diseases such as anxiety." (PMID 35788107, 2022). "Our results may provide a cellular and molecular mechanism to explain the physiological functions of AVP, such as learning and memory, and pathologic disorders like anxiety." (PMID 35788107, 2022). "Therefore, it has been shown that rats over-expressing AVP in the PVN exhibit high levels of anxiety and a depression-like phenotype, which is normalized after a long-term treatment with the antidepressant paroxetine." (PMID 34769501, 2021). "Therefore, AVP administration in the amygdala induced an increase in audible and ultrasonic vocalizations and anxiety-like behaviors." (PMID 34769501, 2021). "As any stress, even a single saline injection, could influence the anxiety measured by MS-USV, we first confirmed that the effect of genetic AVP mutation was still detectable after the mild stress of a saline injection." (PMID 33808441, 2021). "Once over-expressed or over-released, AVP may contribute to hyper-anxiety and disturbed rhythmicity." (PMID 34504149, 2021). "Similarly, RLN3 influences feeding behavior, stress responses, anxiety and memory, and AVP is a regulator of social behavior." (PMID 33834688, 2021). "AVP is predominantly involved in stress adaptation and anxiety." (PMID 36246514, 2021). "It reduced impulsive aggression, fear, depression and anxiety in animal models, blocked the actions of intranasal AVP on aggression/fear circuits in an experimental medicine fMRI study and demonstrated excellent safety in Phase 1 multiple-ascending dose clinical trials." (PMID 33207828, 2020). "If extra-neurohypophysial magnocellular AVP projections modulate anxiety and stress, one might expect they would also modulate activity in the open field test." (PMID 31160697, 2019). "AVP acts through central mechanisms to regulate anxiety (see63 and references therein)." (PMID 31160697, 2019). "AVP is related to not only anxiety but also reward processing." (PMID 31354450, 2019). "This study sought to examine the behavior and OT and AVP fluctuations in dogs in response to a commonly occurring human-dog interaction that might potentially induce anxiety in dogs." (PMID 31779267, 2019). "This suggests that OXT and AVP regulate different types of anxiety." (PMID 31354450, 2019). "In addition, among both men and women, intranasal AVP increases empathic concern in those who received high levels of paternal warmth, as well as anxiety and skin conductance responses to angry faces." (PMID 28871239, 2017).
Anxiety (continued). "While there are three receptor subtypes for AVP (V1A, V1B, and V2), the V1A receptor (AVPR1A), has been suggested to play the dominant role in regulating behaviour and is implicated in the modulation of stress, anxiety, and sociability." (PMID 28821809, 2017). "Similarly, male rats maintained on a diet containing 150 μg/g GEN and daidzein displayed increased anxiety and elevated stress-induced plasma AVP and corticosterone levels." (PMID 28674520, 2017). "OtpR108W/+ mice exhibit increased food intake, weight gain, and anxiety when in novel environments or singly housed, phenotypes that may be partially explained by reduced hypothalamic expression of oxytocin and arginine vasopressin." (PMID 29107289, 2017). "However, several studies reveal that AVP administration can have effects very similar to those of OT, decreasing heart rate, reducing anxiety, and increasing sociability." (PMID 29021768, 2017). "In addition to examining these adult behaviors, we evaluated the blood testosterone levels and the numbers of cells expressing arginine-vasopressin (AVP) in the hypothalamus because they are closely associated with socio-sexual and anxiety-related behaviors." (PMID 27375407, 2016). "It was hypothesized that both AVP and OXT would have preventative effects on social stress-induced deficits in social behavior and increased anxiety and that these effects would be associated with changes in TNFα and/or IFNγ in juvenile F2 females." (PMID 28018290, 2016). "Arginine-Vasopressin (AVP) could counteract these fear (or anxiety) effects by strengthening the PFC activity as a top-down fear/anxiety regulator." (PMID 25852497, 2015). "Furthermore, intranasal administration of AVP increased autonomic responsiveness to threatening social stimuli and increased anxiety in humans." (PMID 26295806, 2015). "Arginine vasopressin (Avp) has been found to affect anxiety, memory and may protect brain cells from excitotoxicity." (PMID 26556046, 2015). "Endogenous AVP increases anxiety while endogenous oxytocin is anxiolytic." (PMID 25853137, 2015). "Further evidence for a role of AVP in anxiety/fear comes from animal research." (PMID 25852497, 2015). "However, the same dose of AVP altered novel cage social play behavior in females, anxiety-related behavior in males, and social recognition in both male and female juvenile rats." (PMID 24982623, 2014). "Low anxiety animals have less AVP in their hypothalamus and display less maternal care." (PMID 24550698, 2014). "These included genes expected to be related to estrous behavior as they influence states like socio-sexual behavior, anxiety, stress and feeding motivation (OXT, AVP, POMC, MCHR1), but also genes whose association with estrous behavior is novel and warrants further investigation." (PMID 21504592, 2011). "However, while AVP expression is clearly under genetic control, the regulation of anxiety-related behavior is more complex." (PMID 19357765, 2009). "In addition, neuropeptides such as oxytocin and arginine vasopressin (argipressin) are mediators of emotional behaviour that may evolve into mood disorders, anxiety, and psychopathological conditions." (PMID 41070359, 2025). "Furthermore, icv administration of AVP induces anxiety-like behavior." (PMID 37760887, 2023). "Based on this and our previous experiments, we hypothesized that KP-13 might alter the CRF and AVP signaling in the amygdala and hippocampus, two brain areas that are involved in the regulation of anxiety-like behavior and express KP and its receptors, as well as CRF and AVP and their receptors." (PMID 37760887, 2023). "Therefore, the purpose of the present study was to assess if KP influences the CRF and AVP expression in the amygdala and hippocampus and if these two stress hormones might mediate KP’s anxiety- and HPA axis-inducing effects." (PMID 37760887, 2023). "This indicates that AVP signaling pathways might mediate KP-13′s anxiety-inducing effect." (PMID 37760887, 2023).
Anxiety (continued). "Consequently, the LS may require AVP signals from both BNST and MeA to increase anxiety‐like behaviours, while other sources of AVP may work to inhibit it." (PMID 34978098, 2022). "Moreover, pharmacological studies suggest that AVP in the LS, a target of BNST AVP cells in mice, may modulate anxiety." (PMID 34978098, 2022). "It expresses several neurohormones such as oxytocin or arginine-vasopressin with conserved function compared to mammals such as the regulation of water homeostasis, the control of blood pressure as well as a role in social behavior and the regulation of anxiety." (PMID 35954455, 2022). "Therefore, targeting the AVP system may contribute to new therapeutic strategies for the treatment of depression and anxiety." (PMID 34679364, 2021). "The association between AVPR1a and reciprocity cannot be explained by the hypothesis that AVP enhances anxiety related to exploitation by others, as there is no risk of being betrayed by others in this case." (PMID 31354450, 2019). "Similarly to anti-OT IgG, plasma levels of AVP-reactive IgG correlated with symptoms of anxiety and somatization and that the levels of CRH-reactive IgG in plasma of healthy subjects correlate positively with obsessive or hypochondriac behavior, but negatively (as anti-AVP IgG) with somatization." (PMID 31866881, 2019). "Although central AVP has been repeatedly implicated in the generation of anxiety states, we did not observe changes in anxiety-like behavior of lesioned males or females in a non-social anxiogenic environment." (PMID 30693316, 2019). "Specifically, AVP may impact anxiety by modulating arousal or vice versa." (PMID 31160697, 2019). "Additionally, AVP promotes anxiety and fearful response to emotional stimuli." (PMID 31354450, 2019). "In addition, AVP release within the amygdala has been observed in response to stressful emotional experiences in male rats, and this release is greater in animals with stronger anxiety behaviors." (PMID 27092094, 2016). "In order to probe further the degrading effects of AVP on musical memory seen in the first session, we asked whether these effects are mediated by some interaction between AVP, the musical memory demands and anxiety and mood variables." (PMID 24151474, 2013). "AVP and OXT confer mostly opposite effects on anxiety and depression-related behavior; however, they have effects in the same direction on social behavior." (PMID 36747195, 2023). "Similar to depression, anxiety and stress can promote increased HPA activity, thereby promoting higher cortisol and arginine vasopressin secretion which subsequently impact insulin levels in the body and promote insulin resistance." (PMID 37823988, 2023). "For this reason, we investigated the gene expression of AVP and OXT receptors in the CeA, BLA and LHb, limbic structures known to regulate anxiety-like and locomotory behaviors and to receive projections from MCNs." (PMID 36817576, 2023). "Forming pair bonds increases AVP-ir in the PVN of male and female zebra finches, whereas pair-bond breakage with concomitant increases in anxiety-like and affiliative behavior also increases PVN AVP-ir in prairie voles." (PMID 36860367, 2023). "Therefore, AVP derived from other sources may modulate anxiety action when released in the septum." (PMID 34978098, 2022). "Anxiety and aggression have multiple overlapping brain pathways involving the HPA axis, arginine vasopressin, gamma-aminobutyric acid, testosterone, and serotonin." (PMID 36465293, 2022). "Besides its antidiuretic renal effects, AVP is a potent neurohormone involved in the regulation of arterial blood pressure, sympathetic activity, baroreflex sensitivity, glucose homeostasis, release of glucocorticoids and catecholamines, stress response, anxiety, memory, and behavior." (PMID 34867449, 2021).
Anxiety (continued). "Women with perceived symptoms of anxiety and depression during pregnancy had altered expression patterns for CRH, HSD11B2, and AVP genes in the placentas, compared to the control population." (PMID 32752005, 2020). "In human patients, AVP is featured with increased vigilance and anxiety, whereas OXT is closely related with reduced anxiety." (PMID 29108272, 2017). "Water-deprivation (WD) for 24 h, which increased the metabolic activity of VPMNNs, also increased anxiety-like behavior measured using the elevated plus maze (EPM) test, and this effect was mimicked by bilateral microinfusion of AVP into the CeA." (PMID 27932956, 2016). "Control and CSS-exposed F1 dams were administered IN saline, AVP, or OXT during lactation and the F2 juvenile female offspring were assessed for basal plasma IFNγ and perseverative, anxiety, and social behavior." (PMID 28018290, 2016). "Consistent with previous reports acute hypernatremia increased Fos induction in AVP and OT expressing neurons in the PVH and SON, an effect that was predictive of increased social interactions but decreased anxiety-like behavior in the elevated plus maze." (PMID 25873866, 2015). "Because AVP typically enhances while OXT reduces anxiety-like behaviors of rats exposed to novel environments, we predicted that AVP would reduce social play while OXT would increase social play in the novel cage." (PMID 24982623, 2014). "We have previously shown that repeated binge-pattern alcohol exposure increased the expression of two critical central regulators of stress and anxiety, corticotrophin-releasing hormone (CRH) and arginine vasopressin (AVP), in adolescent male rats." (PMID 22384198, 2012). "It was postulated that chronic central AVP infusion would alter maternal behavior and growth patterns in dams and their pups exposed to the CSS rodent model for postpartum depression and anxiety." (PMID 24349762, 2012). "In the context of social stress, shared neurobiological mechanisms involving the upregulation of arginine vasopressin (AVP) and oxytocin may play a significant role in the development of comorbid anxiety and AUD." (PMID 41560888, 2026). "We investigated the correlations between six neurochemical markers (serotonin, AVP, CRH, corticosterone, testosterone, and oxytocin) and anxiety-like behaviour in the OFP and EPM, as well as aggressive behaviours in the resident intruder paradigm conducted pre and post the SxAT paradigm." (PMID 40011829, 2025). "For example, in territorial Angolan blue Waxbills, knockdown of BNST AVP reduces social contact primarily between males but does not affect anxiety-like behavior." (PMID 36860367, 2023). "Lesions of AVP cells in SCN of mice did not influence their social behavior but did increase anxiety-like behavior and sucrose consumption in both sexes." (PMID 36860367, 2023). "All these data suggest that KP-13 could affect the AVP and CRF signaling pathways and that might be responsible for its effect on the HPA axis and anxiety-like behavior." (PMID 37760887, 2023). "A large literature has shown that various neuropeptides, including corticotropin-releasing factor (CRF), cholecystokinin (CCK), arginine vasopressin (AVP), oxytocin, orexin, neuropeptide Y (NPY), neuropeptide S (NPS), galanin, and neurokinins, such as substance P, affect anxiety-related behaviors." (PMID 36623804, 2023). "This suggests that KP-13 alters the AVP and CRF signaling and that might be responsible for its effect on the HPA axis and anxiety-like behavior." (PMID 37760887, 2023). "In agreement with the effects of BNST AVP cell ablation, we observed no changes in anxiety‐like behaviour following BNST AVP knockdown." (PMID 34978098, 2022). "We also investigate the impact of exercise on reducing subjectively perceived stress, craving level, negative reinforcement, anxiety, sleep quality, plasma OT, AVP, and cortisol levels." (PMID 36569629, 2022).
Anxiety (continued). "As an auxiliary treatment, exercise improves the plasma OT, AVP and cortisol levels of opioid addicts, and reduces their subjective perceived stress level, desire, negative reinforcement level, anxiety level, and sleep quality." (PMID 36569629, 2022). "Moreover, hyper-anxious rats and mice (based upon their performance on elevated plus maze; high anxiety behavior, HAB; low anxiety behavior, LAB) also had higher AVP mRNA expression in their PVN together with disturbances in their HPA axis." (PMID 34502322, 2021). "A previous study showed that AVP increases anxiety levels in males, as assessed by the EPM test, but did not affect females." (PMID 34045941, 2021). "Oxytocin (OXT) and arginine-vasopressin (AVP) are two neuropeptides synthesized in the supraoptic nucleus (SON) and paraventricular nucleus (PVN) of the hypothalamus and are related to social interaction, social memory and anxiety in mammals." (PMID 30971895, 2019). "Despite over thirty years of indirect evidence implicating sexually-dimorphic arginine vasopressin (AVP) cells within the bed nucleus of the stria terminalis (BNST) in the control of social and anxiety-related behavior in mammals, the function of these cells has never been directly tested." (PMID 30693316, 2019). "A previous study found that OT in the PrL region of the mPFC decreased anxiety regardless of sex and that neither AVP nor OTR-A affected anxiety-like behavior." (PMID 31084703, 2019). "During an RI test, release of AVP, specifically in the hypothalamic mediolateral septum, was found to regulate intermale aggression in laboratory rats specifically bred for low (LAB)- or high (HAB)- anxiety‐related behavior." (PMID 31866881, 2019). "While AVP and OXT have been reported to have similar effects on anxiety and social behavior in some species, the present results support the hypothesis that they have unique, behaviorally specific programing effects on offspring." (PMID 28018290, 2016). "It was hypothesized that maternal AVP and OXT treatment would have preventative effects on social stress-induced deficits in offspring anxiety and social behavior and that these effects would be associated with changes in interferon-γ (IFNγ)." (PMID 28018290, 2016). "During anxiety and OCD, plasma and CSF levels of AVP are significantly increased." (PMID 25853137, 2015). "AVP enhanced anxiety-related behavior in males (tested on the elevated plus-maze), but failed to do so in females, suggesting that exogenous AVP alters social play and anxiety-related behavior via distinct and sex-specific mechanisms." (PMID 24982623, 2014). "Even though AVP in the SCN plays an important role in adjusting circadian rhythms, it does not appear to play a critical role in social behavior but may, instead, regulate reward and anxiety-like behavior." (PMID 36860367, 2023). "Indeed, high anxiety rat lines do not increase AVP release in the PVN during maternal aggression but do increase it in the central amygdala (CeA), where V1aR antagonists can reduce maternal aggression." (PMID 36860367, 2023). "BNST AVP knockdown in male, but not female, mice reduced social approach and communicative behaviors directed toward same‐sex conspecifics, without changing offensive attacks, anxiety‐related behaviors, and overall activity." (PMID 34978098, 2022). "Our results show the emergence of a stress response, highlighted by genes known to be involved in the HPI axis or coding for neurohormones (oxytocin, arginine-vasopressin) and neurotransmitters (serotonin, dopamine but not acetylcholine) that play a role in the regulation of anxiety-like behavior." (PMID 35954455, 2022). "AVP may not regulate the anxiety related to exploitation by others, but rather anxiety regarding the loss of money." (PMID 31354450, 2019).